PDRG1 (p53 and DNA damage regulated 1)
Description:
May play a role in chaperone-mediated protein folding.
Synonyms: C20orf126; PDRG; dJ310O13.3
Tractability: PROTAC: ubiquitination databases record sites on it; its protein half-life has been measured.
Gene: Protein-coding gene on chromosome 20 (31,944,337 to 31,952,069, reverse strand). Ensembl gene ENSG00000088356.
Subcellular location: Cytoplasm
Subcellular location (Human Protein Atlas): Actin filaments
Gene Ontology:
Molecular function: protein binding
Biological process: protein folding; protein stabilization
Cellular component: RPAP3/R2TP/prefoldin-like complex; protein folding chaperone complex; cytoplasm; prefoldin complex
Genetic constraint (gnomAD): Loss-of-function variants: 14 observed, 16.23 expected, observed/expected ratio (o/e) 0.86, 90% interval 0.57 to 1.35. The upper end of that interval is the gene's LOEUF score, 1.35, which puts it in group 5 of 6, group 1 being the genes least tolerant of losing a copy. Missense variants: 177 observed, 159.27 expected, observed/expected ratio (o/e) 1.11, 90% interval 0.98 to 1.26. Synonymous variants: 65 observed, 58.46 expected, observed/expected ratio (o/e) 1.11, 90% interval 0.91 to 1.37.
Homologues: Orthologues: macaque PDRG1 (100% identical), chimpanzee PDRG1 (99% identical), dog PDRG1 (97% identical), pig PDRG1 (96% identical), guinea pig PDRG1 (95% identical), rabbit PDRG1 (93% identical), mouse Pdrg1 (92% identical), rat Pdrg1 (89% identical), zebrafish pdrg1 (58% identical), Drosophila melanogaster Pdrg1 (28% identical), Caenorhabditis elegans T07D4.5 (20% identical).
Diseases named in the same sentence as PDRG1 in open-access papers:
PDRG1 is named in the same sentence as 20 diseases in open-access papers, as found by Europe PMC text mining. Sharing a sentence is not in itself a finding about the gene and the disease. The quoted sentences say what the papers report.
hepatoma (4 papers, 2016 to 2026). "Silencing of PDRG1 in hepatoma cells downregulates genes associated with tumor progression according to GO pathway analysis." (PMID 34065390, 2021). "The binding of MATs and their putative collaboration with PDRG1 was proposed to control the nuclear methylation status in human hepatoma; therefore, we explored the possible role of PDRG1." (PMID 37240447, 2023). "Silencing of Pdrg1 expression in hepatoma cells alters their steady-state expression profile on microarrays, downregulating genes associated with tumor progression according to GO pathway analysis." (PMID 27548429, 2016). "For this purpose, rat hepatoma H35 cells were chosen given that RTqPCR results demonstrated their elevated Pdrg1 levels and that nuclear accumulation of MATα1 has been described in hepatoma cells." (PMID 27548429, 2016). "Increased Pdrg1 expression is detected in acute liver injury and hepatoma cells, together with decreased Mat1a expression and nuclear accumulation of MATα1." (PMID 27548429, 2016). "We next examined hepatic Pdrg1 expression in two animal models of liver disease and in hepatoma cells." (PMID 27548429, 2016). "Furthermore, MATα1 overexpression is known to induce DNA hypermethylation in hepatoma cells, the preventive effect exerted by coexpression with PDRG1 confirming the relevance of the interaction for the control of nuclear methylations." (PMID 27548429, 2016). "Therefore, the changes induced in hepatoma cells by Pdrg1 downregulation seem to follow an opposite pattern than those exhibited by Mat1a-/- or Gnmt-/- livers with hepatic damage (esteatosis, hepatocellular carcinoma), which show induced or normal lipogenesis, respectively." (PMID 27548429, 2016). "PDRG1 was found to interact with MAT2A protein to translocate into the nuclei in cell lines, including CHO (Chinese hamster ovary), COS-7 (monkey kidney), H35 (rat hepatoma), N2a (mouse neuroblastoma) and HEK-293T (human kidney)." (PMID 37240447, 2023). "The lack of significant changes in Mat1a or Mat2a expression in our silenced clones do not exclude the possibility that total suppression of Pdrg1 expression enhances MAT levels and, in turn AdoMet concentrations, known to be pro-apoptotic in hepatoma cells." (PMID 27548429, 2016).
hemangioma (3 papers, 2020 to 2024). A benign vascular lesion characterized by the formation of capillary-sized or cavernous vascular channels. "FOXD2-AS1 is highly expressed in proliferative hemangioma tissues, and its knockdown inhibits cell proliferation, migration, invasion, and colony formation through the miR-324-3p/PDRG1 pathway." (PMID 34872450, 2021). "LncRNA FOXD2-AS1 promotes hemangioma progression through the miR-324-3p/PDRG1 pathway." (PMID 39397896, 2024). "Besides, a previous study revealed that LncRNA FOXD2-AS1 promotes hemangioma progression via regulating DNA damage regulated 1 (PDRG1)." (PMID 39397896, 2024).
hepatic diseases (3 papers, 2016 to 2023). "Altogether, the results unveil the role of PDRG1 in the control of the nuclear methylation status through methionine adenosyltransferase binding and its putative collaboration in the progression of hepatic diseases." (PMID 27548429, 2016). "The fact that PDRG1 immunoprecipitates with nuclear MATα1, suggested that this interaction may be more relevant in extrahepatic tissues or in hepatic disease, two environments in which MATα1 accumulates into this subcellular compartment." (PMID 27548429, 2016). "The protein PDRG1 has been proposed to control nuclear methylation status through MAT binding and its putative collaboration in the progression of hepatic diseases." (PMID 37240447, 2023).
lung carcinoma (3 papers, 2017 to 2020). "PDRG1 was confirmed as a direct target of miR-324-3p, which is recognized as an oncogene in cancers including gastric cancer and lung cancer." (PMID 32489325, 2020).
osteosarcoma (3 papers, 2020 to 2022). A usually aggressive malignant bone-forming mesenchymal neoplasm, predominantly affecting adolescents and young adults. "miR-519a-3p was demonstrated to suppress the growth, invasion, and migration via PARP1 in ovarian cancer, and miR-519a-3p served as a target of LINC01419 to repress the proliferation and metastasis of osteosarcoma cells via PDRG1." (PMID 35350655, 2022). "LncRNA LINC01419 was noted to regulate PDRG1/miR-519a-3p axis to induced osteosarcoma cell progression." (PMID 34102610, 2021).
colon cancer (2 papers, 2013 to 2020). "Interestingly PDRG1 protein expression was also shown to be increased in several cancers (colon, rectum, ovary, lung, stomach, breast and uterus) and depletion of PDRG1 in colon cancer cell lines was shown to induce a decrease in cell proliferation." (PMID 23667685, 2013).
gastric cancer (2 papers, 2020). A primary or metastatic malignant neoplasm involving the stomach. "In addition, PDRG1 functioned as an proliferation-facilitator in gastric cancer." (PMID 32390762, 2020).
ovarian cancer (2 papers, 2017 to 2022). A primary or metastatic malignant neoplasm involving the ovary.
bladder cancers (1 paper, 2023).
breast carcinoma (1 paper, 2021). "The binding of methionine adenosyltransferase and its putative collaboration with PDRG1 was proposed to control of the nuclear methylation status in HCC; we therefore explored the possible role of PDRG1 in breast cancer." (PMID 34065390, 2021). "However, Kaplan–Meier survival analyses using RNA-seq data from the GEPIA indicated that Pdrg1 gene expression is not related to breast cancer survival." (PMID 34065390, 2021).
colorectal cancer (1 paper, 2025). A primary or metastatic malignant neoplasm that affects the colon or rectum. "Similarly, the silencing of PDRG1 in colorectal cancer cells decreased vitality, invasion, and migration, and induced cell apoptosis and G0/G1 phase arrest." (PMID 39851503, 2025).
liver cancer (1 paper, 2021). An epithelial or non-epithelial malignant neoplasm that arises from the liver.
osteoarthritis (1 paper, 2025). A noninflammatory degenerative joint disease occurring chiefly in older persons, characterized by degeneration of the articular cartilage, hypertrophy of bone at the margins and changes in the synovial membrane. "Genes associated with DDH and osteoarthritis include FRZB, CX3CR1, ASPN, DKK1, PDRG1, GDF5, UQCC1, and TGF-β1." (PMID 41019141, 2025). "A study of 770 cases of patients with DDH from the UK found a significant positive correlation of PDRG1 with DDH susceptibility using a linkage disequilibrium score to determine PDRG1 overlap between DDH and osteoarthritis (P = .0047)." (PMID 41019141, 2025).
Wilson disease (1 paper, 2016). A very rare inherited multisystemic disease presenting non-specific neurological, hepatic, psychiatric or osseo-muscular manifestations due to excessive copper deposition in the body. "Livers of 9-week old LEC rats, a model of Wilson disease, exhibited a moderate decrease in Mat1a expression (~20%) that was not followed by changes in Pdrg1 expression as compared to the controls." (PMID 27548429, 2016).
cancer (10 papers, 2013 to 2025). A tumor composed of atypical neoplastic, often pleomorphic cells that invade other tissues. "In fact, Sema3c, Id1, Cxcl1 and Ctgf, which are upregulated in a variety of cancer types, were downregulated upon Pdrg1 silencing." (PMID 27548429, 2016). "PDRG1 expression was found to be correlated with higher or more advanced tumor stages, suggesting it could play a role in cancer progression." (PMID 28057028, 2017). "Additionally, genes normally upregulated in several types of cancer cells (Sema3c, Id1, Cxcl1, Ctgf) appear downregulated by Pdrg1 silencing." (PMID 27548429, 2016). "A putative explanation may derive from results on miR-214 expression in cancer, where downregulation of this microRNA inversely correlates with Pdrg1 expression, and accumulation of Polycomb Ezh2 methyltransferase is detected." (PMID 27548429, 2016). "While recent progress has been made in understanding the functional roles of PDRG1 in cancer cell biology, no studies to date have investigated its expression and role in regulating endothelial cell (EC) functions." (PMID 39851503, 2025). "Comparison with genes that are altered by etoposide and gemcitabine in Mero-14 cell line indicated that the PDRG1 gene is upregulated in cells exposed to DNA damage, and although its role in cancer development is not well described potential drugs that can target it indirectly are available." (PMID 30316293, 2018). "Additionally, aberrant DNA methylation is a well-established characteristic of cancer cells, and recent studies demonstrated global DNA hypomethylation correlating with enhanced expression of PDRG1 in a variety of human non-hepatic tumors." (PMID 27548429, 2016).
tumor (9 papers, 2016 to 2026). "PDRG1 knockdown also decreased tumor growth and metastasis and enhanced apoptosis-related protein expression." (PMID 39851503, 2025). "This study uncovered the high level and tumor-facilitating role of PDRG1 in OS cells." (PMID 32390762, 2020). "Furthermore, the tumor sizes of the injected NPC cells with HIF1α or PDRG1 overexpression were significantly larger than those of the control cells, as shown in the xenograft mice model." (PMID 28057028, 2017). "In addition, the stress regulation of PDRG1 was further studied and found to be induced by genotoxic stress (DNA damage), and its knock down in human colon cancer cells resulted in a significant reduction in tumor cell growth." (PMID 29301330, 2018). "Finally, altogether the results presented in this work made us hypothesize that the oncogenic role of PDRG1 may rely, at least in part, to its counteracting effect on repression of key genes for tumor progression through interaction with MAT I." (PMID 27548429, 2016). "Functionally, PDRG1 enhanced HCC cell proliferation, migration, invasion, colony formation, and tumor growth in vivo." (PMID 41943853, 2026). "PDRG1 was significantly upregulated in HCC tumor tissues compared with adjacent non-tumor liver tissues and was associated with worse patient survival." (PMID 41943853, 2026).
PDRG1 also shares sentences with these, for which no sentence is quoted: nasopharyngeal carcinoma (2 papers); glioblastoma multiforme (1); male infertility (1); neuroblastoma (1).